LEP (leptin)
Diseases named in the same sentence as LEP in open-access papers (continued):
Sharing a sentence is not in itself a finding about the gene and the disease.
cancer (continued). "Leptin increases the expression of IL-8 in M2 macrophages and leads to the migration and invasion of cancer cells." (PMID 39192979, 2024). "Some obese/overweight cancer patients experience better prognoses and responses to immunotherapy due to the “leptin paradox” than their normal‐weight counterparts." (PMID 38405061, 2024). "Leptin and Ob-R concentrations are positively correlated with cancer invasiveness, metastasis, poor prognosis, and aggressive cancer presentation." (PMID 38255203, 2024). "This interplay of leptin, IL-1 and Notch upregulated ligands, receptors and relevant genes, thereby enhancing the proliferation and migration of cancer cells." (PMID 39201370, 2024). "Leptin, a hormone produced by fat cells, has been studied in relation to cancer; it regulates processes like appetite, metabolism, and energy balance." (PMID 38534979, 2024). "Leptin can also interact with other pathways, such as insulin-like growth factor 1 and estrogen, that further promote cancer growth." (PMID 38534979, 2024). "The adipokines leptin and adiponectin have also been found to affect various inflammatory markers, pathways within TAMs, and the tumor microenvironment that lead to carcinoma progression." (PMID 38611081, 2024). "Even though leptin shows opposite expression patterns in different cancer types, its gene expression is upregulated in response to TNF-α and IL-1 stimulation 91-94, which are elevated in the serum of PC patients and correlated with poor prognosis 95-97." (PMID 37554282, 2023). "First, adiposity tissue, especially visceral adipose can increase concentrations of serum insulin and insulin-like growth factor- I (IGF-I), and lead to leptin and adiponectin secretion, which play important roles in the pathogenesis of cancer." (PMID 36991401, 2023). "Increased secretion of hormones, such as leptin, adipsin, and survivin, by obese ASCs is also involved in cancer development." (PMID 36766689, 2023). "In fact, leptin physiologically regulates energy metabolism, appetite, and reproduction, and several studies have also described the role of leptin in affecting cancer development and progression." (PMID 37509120, 2023). "Leptin is known to be protumorigenic and proangiogenic, and to act directly on cancer cells to promote their proliferation and inhibition of programmed cell death." (PMID 37629396, 2023). "Leptin is secreted by adipocytes, fibroblasts and cancer cells, with autocrine, paracrine and endocrine effects in cancers." (PMID 37233716, 2023). "By activating both a non-specific tyrosine phosphatase inhibitor and a specific PTP1B inhibitor, it significantly reduces the secretion of MMP-2 and MMP-9 from leptin-stimulated oesophageal cancer cells, inhibiting cancer invasion through this mechanism." (PMID 37686525, 2023). "Some of the adipokines participate in the anti-cancer activity, such as adiponectin and some present tumorigenic properties, such as leptin." (PMID 36835413, 2023). "Meanwhile, several pieces of evidence have shown that leptin, whose circulating levels proportionally increase with fat mass, directly or indirectly impacts the biology of several cancers." (PMID 37509120, 2023). "Tumor factors can regulate the expression of adipokines with oncologic potential, such as leptin and adiponectin, which interact with cancer cells through TME as well." (PMID 37686525, 2023). "Secondly, the increasing levels of serum leptin, via the activation of the PI3K, trigger an increase in cell growth and proliferation, which eventually lead to cancer formation if accompanied with other mutations affecting oncogenes or tumor suppressor genes." (PMID 37892180, 2023). "Together, these data indicate that as a target of p73, Leptin mediates p73γ in tumor promotion and altered lipid metabolism and that the p73γ-Leptin pathway can be targeted for cancer management." (PMID 37650871, 2023).
cancer (continued). "In cancer, leptin was demonstrated to promote mitogenic, antiapoptotic, and proangiogenic pathways which are involved in carcinogenic processes." (PMID 37444627, 2023). "Evidence supporting indirect effects using this approach, as in this study for adulthood leptin, has been found previously for various cardiovascular and site-specific cancer endpoints." (PMID 37878001, 2023). "In cancer diseases, it is necessary to know in detail the cellular events promoted by leptin, and thus act against these targets that promote invasion, migration, metastasis, and angiogenic processes." (PMID 36674935, 2023). "Leptin-targeting drugs can affect different cell types, including endothelial cells, adipocytes, cancer cells with a less aggressive phenotype, and immune cells by decreasing macrophage recruitment, phagocytic activity, and cytokine production." (PMID 36835413, 2023). "Leptin favors cancer cell proliferation and invasion, influencing cancer cell differentiation and migration, stimulating angiogenesis, and inhibiting cancer cell apoptosis." (PMID 37048738, 2023). "The first inhibitory effect of leptin treatment in human cancer cell lines was reported in pancreatic cells." (PMID 36674935, 2023). "In obese cancer patients, there can be changes in analytes such as adiponectin, adipokines, leptin, ceruloplasmin, etc.." (PMID 37378223, 2023). "Altered levels of leptin and adiponectin, an imbalance in their production, impaired assembly, secretion and signal transduction are crucial factors for the development of cancer and induce a variety of changes leading to carcinogenesis." (PMID 37686525, 2023). "This prevents atherosclerosis, cellular senescence and the development of cancers driven by hypersecretion of inflammatory adipokines, including leptin." (PMID 37233716, 2023). "Leptin signaling is also found to promote cancer progression, including cell proliferation, metastasis, angiogenesis, and chemoresistance." (PMID 37650871, 2023). "The influence of leptin plasma levels on the development of cancer has been established in patients with breast cancer and endometrial cancer." (PMID 37048738, 2023). "The biochemical mechanisms that outline the development of cancer in states of metabolic imbalance are growing, with the mTOR signaling pathway and hormones such as leptin serving as scaffolds for pharmacological intervention." (PMID 37626871, 2023). "In another report, inhibition of leptin secretion by a neutralizing antibody demonstrated its efficacy in reducing ob-ASC-mediated cancer proliferation." (PMID 36766689, 2023). "Recent studies suggest that leptin plays an important role in tumorigenesis, angiogenesis and metastasis of many cancers." (PMID 37378223, 2023). "Several preclinical studies have identified plant-derived compounds that inhibit cancer growth by targeting leptin signaling, including honokiol, silibinin, and curcumin." (PMID 37895840, 2023). "Cancer cells interact with adipocytes, which provide the TME with FFA, leptin, ketone bodies, and other macromolecules that alter cancer cell metabolism." (PMID 37289328, 2023). "The aim is to clarify the various mechanisms that link leptin, adiponectin and carcinogenesis for the future potential use of these adipokines in cancer diagnostics and therapeutics." (PMID 37686525, 2023). "Other emerging studies put the role of elevated leptin and decreased adiponectin levels in obese patients in the spotlight of cancer initiation and promotion." (PMID 37629396, 2023). "Many studies have reported that one of the leptin-induced cancer-cell invasion mechanisms is upregulating MMP expression." (PMID 37686525, 2023). "One of the explanations for this dependency is the secretion of pro-inflammatory and pro-cancer cytokines such as leptin." (PMID 37444627, 2023). "Leptin actions in cancer progression are intensified through crosstalk with multiple oncogenes and proinflammatory interleukins adjacent to the tumor, favoring T-helper 1 responses." (PMID 36674935, 2023).
cancer (continued). "Adipocytes-derived leptin regulates gene expression related to cancer progression, such as adhesion, invasion, angiogenesis, signal transduction and apoptosis." (PMID 37620316, 2023). "Leptin and different isoforms of its receptor are abnormally expressed in cancer cells and tumor-adjacent areas." (PMID 36674935, 2023). "The results of research in recent years indicate that leptin is also produced by cancer cells of the large intestine and breast." (PMID 36981858, 2023). "CA19-9, ferritin, and HER3 can function as cancer drivers, and CA15-3, ferritin, leptin, and other markers used here are implicated in pathways affecting apoptosis, angiogenesis, and metastasis." (PMID 37857666, 2023). "Afterwards, other studies showed changes in circulating leptin levels, together with a decrease in one or more isoforms of its receptor in different cancer types." (PMID 36674935, 2023). "Concerning the mechanisms whereby the fasting-induced reduction in insulin, IGF1 and leptin mediates cancer cell sensitization to CBIs, we first focused on the expression of enzymes from the cholesterol biosynthesis pathway." (PMID 37907500, 2023). "As demonstrated by previous investigations, leptin acts as a proliferative and angiogenic factor in cancer cells." (PMID 37942199, 2023). "Studies have shown that the stringent binding affinity of leptin/Ob-R and the overexpression of leptin/Ob-R and its targets in cancer cells make it a unique drug target for the prevention and treatment of CRC, especially in obese colorectal patients." (PMID 36160034, 2022). "These properties joined with the ability of leptin to promote angiogenesis, confer to this adipokine the main role as a growth factor for cancer cells." (PMID 35681689, 2022). "Taking this into account, adiponectin has opposite effects to leptin in cancer, promoting apoptosis and reducing proliferation, migration, and inflammation." (PMID 35164764, 2022). "Accumulating evidence suggests a role for LEP in cancer development and progression by interacting with several oncogenic pathways and shaping the immune microenvironment." (PMID 36291602, 2022). "IL-6 administration also temporarily increased leptin levels in cancer patients in a dose-dependent manner." (PMID 36558477, 2022). "A variety of mechanisms have been proposed to mediate the link between metabolism and cancer, including leptin, adiponectin, resistin, inflammatory cytokines, reactive oxygen species, sex hormones, and others." (PMID 35595952, 2022). "Leptin, interferon‐γ, IL‐1β, IL‐10, adiponectin, and ghrelin did not demonstrate any significant difference between groups when individuals with cancer cachexia were compared against non‐cachectic patients or healthy participants." (PMID 35080147, 2022). "Rather, we uncovered a cancer link to the leptin–LEPR signalling pathway that becomes activated de novo downstream of an oncogenic HRAS(G12V)-induced change within otherwise normal skin stem cells." (PMID 36450983, 2022). "Upregulation of leptin disrupts epithelial polarity and sensitizes non-cancer cells to proliferative stimuli to expand the stem cell/progenitor population, subsequently initiating early stages of malignancy." (PMID 35186923, 2022). "Leptin is an activator of cell proliferation, an antiapoptotic molecule, and an inducer of cancer stem cells in many cell types." (PMID 36160034, 2022). "In contrast to leptin’s effects on cancer, APN has been demonstrated to exert a protective role in the course of different malignancies, especially BC." (PMID 35681689, 2022). "Leptin also participates in the maintenance and support of cancer stem cells through the STAT3 pathway, either by regulating the lipid metabolism or by increasing the expression of stemness transcription factors NANOG, SOX2, and OCT4." (PMID 36291097, 2022). "Accumulating evidence suggests that leptin contributes to various aspects of tumor progression and metastasis in multiple cancers such as breast, oral, and pancreatic cancers." (PMID 35778755, 2022).
cancer (continued). "The invasion of fat by cancer cells is known to secrete various adipokines such as leptin, adiponectin, IL-6, CCL2, and CCL5." (PMID 35123536, 2022). "Leptin, an adipocytokine, promote cancer progression through multiple mechanism, including various metabolic regulations in cancer cells." (PMID 35628510, 2022). "Surpassing the mere detection of cancer, leptin expression was significantly correlated to the stage of metastasis, as well as the degree of lymph node development." (PMID 35628271, 2022). "Leptin has been shown to increase the proliferative and invasive capacity of Barrett cell lines, and APN has been shown to block the cancer-promoting effects of leptin in experimental models." (PMID 35409299, 2022). "Circulating levels of adiponectin and leptin are in accordance with their cancer biological function." (PMID 35073877, 2022). "In turn, leptin participates in controlling energy balance, metabolism, immune, tumorigenesis, and cancer metastasis." (PMID 35111566, 2022). "Many studies have investigated the impacts of leptin on human cancers, such as proliferation and metastasis." (PMID 35628510, 2022). "Leptin is associated with endocrine metabolism, as well as the regulation of appetite and energy expenditure; thus, decreased sensitivity to leptin may lead to metabolic disorders and cancer, with its involvement demonstrated in many carcinogenesis-related signal pathways." (PMID 35563103, 2022). "Mechanistically, we demonstrated that leptin drove cancer development through EGFR signaling in NPC." (PMID 35778755, 2022). "Leptin was shown to promote cancer progression and metastasis by regulating the EMT, cell adhesion to the extracellular matrix (ECM), and proteolysis of the ECM compounds." (PMID 35406551, 2022). "Leptin signalling plays an important role in tumour progression and maintenance of the cancer stem cell population by upregulating the cancer stem cell signalling pathways, Notch and Wnt." (PMID 35159385, 2022). "Accordingly, increased leptin triggers cancer formation by increasing insulin growth factor (IGF-1) and increasing cell growth through activation of PI3K/AKT/mTOR signaling and suppressing apoptosis." (PMID 37529006, 2022). "For all cancer sites, cases were more likely to have BMI≥30 kg/m2, and higher median values for leptin, CRP, and fasting insulin relative to controls." (PMID 35048536, 2022). "Leptin, an adipokine, is an essential factor that increases tumor cell proliferation and angiogenesis in cancer cases." (PMID 37529006, 2022). "It is noteworthy to mention the interplay between leptin and adiponectin, as it is well documented that a metabolic dysregulation resulting in hypoadiponectinemia and hyperleptinemia favors cancer cell growth via both systemic and local mechanisms." (PMID 35406450, 2022). "The leptin-leptin receptor signaling is also known to play a critical role in cancer progression, including cell proliferation, metastasis, angiogenesis, and chemoresistance." (PMID 36381236, 2022). "The demonstration that leptin regulates cancer cell autophagy highlights the importance of autophagy in the anti-apoptotic, proliferative and migratory effects, and metabolic reprogramming, associated with leptin-mediated tumor progression." (PMID 36291097, 2022). "In vitro studies revealed that leptin sustained mitochondrial respiration to produce ATP by fostering the use of fatty acids as a fuel for producing energy in cancer cells." (PMID 36361728, 2022). "Both insulin and leptin have been shown to promote the growth of cancer cells, whilst leptin also functions as an inflammatory cytokine." (PMID 35681688, 2022). "Leptin was found to influence cellular differentiation and the progression of PCa among other cancers." (PMID 35406450, 2022). "Substantial literature suggests that leptin plays a key role in cancer progression inhibition, called the “leptin paradox”." (PMID 35628510, 2022).
cancer (continued). "In cancer cell lines, leptin can be both mitogenic and antiapoptotic, and it is involved in carcinogenesis by initiating tumor cell proliferation, angiogenesis, and metastasis." (PMID 35053431, 2022). "Inflammatory cytokines, such as adiponectin, resistin and leptin, have been shown to correlate with the development, progression and mortality of various types of cancer." (PMID 36497484, 2022). "Currently, there lacks research examining the effect of fasting-related decreases in leptin and increases in adiponectin on mammary epithelial polarization, cancer stem cell activity, autophagy, invasion, and metastasis." (PMID 35186923, 2022). "In this sense, leptin is able to target its own receptor, which is over-expressed in a range of cancers, including CRC, leading to enhanced drug delivery properties." (PMID 36361914, 2022). "In obese patients, higher leptin levels were found to promote the proliferation of cancer cells and metastasis." (PMID 35328822, 2022). "Fourthly, the genetic instruments for leptin, adiponectin, and fasting insulin, explained only a small fraction of the genetic variance in these traits, which, might have resulted in low statistical power and missed associations between these traits and certain cancers." (PMID 36558416, 2022). "In hepatocarcinoma, adiponectin can abolish the effects of leptin by inhibiting the proliferation and invasion of cancer cells." (PMID 35625629, 2022). "Murphy and colleagues identified leptin as a potential therapeutic target for neutralization to enhance immunotherapy efficacy in obese cancer patients." (PMID 35164764, 2022). "Adipokines are fat-derived factors and include leptin, adiponectin, resistin, and visfatin for which a role in cancer cachexia has been suggested." (PMID 35406586, 2022). "Leptin is a key factor in signal transduction and is involved in tumorigenesis and cancer metastasis." (PMID 35111566, 2022). "Leptin has been suggested to strongly take part in cancer onset and proliferation, by activating several growth signaling pathways such as PI3K/Akt, MAPKs (ERK1/2), and JAK/STAT3, which drive cell-cycle progression acting on different target genes." (PMID 35681689, 2022). "Abundant expression of leptin, including its mRNA expression levels, have been found in several types of human cancer cells, as well as tumor biopsies." (PMID 35778755, 2022). "Leptin is overexpressed in breast cancer and many other types of cancer, has a role at different levels and participates in cancer progression." (PMID 35395810, 2022). "Leptin, CRP, fasting insulin, and estradiol appear to mediate the effect of high BMI on cancer risk to different extents, with likely varying degrees of importance between cancers." (PMID 35048536, 2022). "As such, it was shown that blocking leptin signaling delayed the emergence of castration-resistant PCa in a murine model of PCa, as well as reduced tumor vascularity, and altered cancer cell apoptosis and energetics." (PMID 35406450, 2022). "The levels of leptin have been reported to correlate with greater adiposity in humans, as well as with a higher prevalence of cancers in obese individuals." (PMID 35328822, 2022). "Particularly, leptin signaling enhances several cancer-promoting pathways, including cancer growth, proliferation, migration, angiogenesis, metabolism, and inflammation." (PMID 35406450, 2022). "Several studies have suggested a role for leptin in the early events that lead to cancer development." (PMID 33859943, 2021). "Further studies will be needed to gain better insights into the role of cancer cell‐specific metabolism in tumor growth by leptin." (PMID 33226729, 2021). "Recently, several studies have been conducted to study the efficacy of leptin with some anticancer drugs such as doxorubicin, which treat a wide range of cancers." (PMID 35027962, 2021).